ALDH2 (aldehyde dehydrogenase 2 family member)
Diseases named in the same sentence as ALDH2 in open-access papers (continued):
Sharing a sentence is not in itself a finding about the gene and the disease.
diabetic cardiomyopathy (17 papers, 2014 to 2025). Diabetic cardiomyopathy is a disorder of the heart muscle in people with diabetes. "ALDH2*2 is associated with increased oxidative stress in diabetes and can be linked to diabetic cardiomyopathy." (PMID 29677191, 2018). "Taking diabetic cardiomyopathy as an example, ALDH2 is extensively activated to detoxify 4-HNE and maintain cardiomyocyte survival, while impaired ALDH2 activity results in massive cardiomyocyte death, lethal inflammation, and severe cardiac dysfunction." (PMID 40968356, 2025). "Studies have shown that α-LA restores ALDH2 activity through reduction of disulfide at its active site in diabetic cardiomyopathy and acute MI/R injury, thus restoring ALDH2 activity and improving nitrate tolerance." (PMID 35645834, 2022). "The development of small-molecule ALDH2 activator provides an opportunity for treating diabetic cardiomyopathy." (PMID 33805825, 2021). "The development of small-molecule ALDH2 activators promises a potential treatment for diabetic cardiomyopathy." (PMID 33805825, 2021). "Recent studies have reported biological roles of ALDH2 in ischemic heart, diabetic cardiomyopathy, and cardiac aging." (PMID 33805825, 2021). "Our findings highlighted the therapeutic potential of ALDH2 activation for treating diabetic cardiomyopathy." (PMID 33805825, 2021). "ALDH2 has a role in the protection against diabetic cardiomyopathy, possibly via an Akt-GSK3b-mediated route, lending ALDH2 therapeutic promise in the management of diabetic complications." (PMID 31234367, 2019). "And more, we also found that upregulation of ALDH2 played a protective effect in myocardial ischemia and reperfusion injury and diabetes cardiomyopathy." (PMID 27547765, 2016). "This, however, is the first report to implicate reduced ALDH2 activity and impaired mitochondrial respiratory reserve capacity in an animal model of diabetic cardiomyopathy." (PMID 27736868, 2016). "In this study, STZ-induced diabetic mice were treated with AD-9308 to examine whether activation of ALDH2 could reverse diabetic cardiomyopathy." (PMID 33805825, 2021). "In addition, ALDH2 has been reported to protect myocardial function through an AMPK-dependent autophagy activation axis in an experimental diabetic cardiomyopathy model." (PMID 30671488, 2018). "Furthermore, in transgenic mice, overexpression of ALDH2 has been shown to be protective against streptozotocin-induced diabetic cardiomyopathy." (PMID 27547765, 2016). "The results suggested that with low-dose ethanol intervention, enhanced ALDH2 expression can antagonize the happening of myocardial fibrosis in diabetic cardiomyopathy, which may be relevant with downregulating the JNK pathway." (PMID 27547765, 2016). "A recent study has found that aldehyde dehydrogenase 2 (ALDH2) can activate the PI3K/AKT/mTOR pathway to alleviate ischemia and reperfusion injury in diabetic cardiomyopathy." (PMID 38283744, 2023). "Treatment with ethanol at low concentration can protect the heart by upregulating ALDH2 and downregulating the JNK signaling pathway against myocardial fibrosis in diabetic cardiomyopathy." (PMID 27547765, 2016). "ALDH2*2 mutant mice with T2DM exhibit significantly worse cardiac function compared to their non-mutant counterparts, further highlighting the clinical relevance of ALDH2 dysfunction in diabetic cardiomyopathy." (PMID 40723901, 2025). "In the rat model of diabetic cardiomyopathy, ALDH2 activation by low concentration of ethanol may regulate the current and protein expression of TASK-1 to reduce myocardial injury and fibrosis, thus playing a protective role in diabetic cardiomyopathy." (PMID 39534859, 2024).
Cognitive impairment (16 papers, 2012 to 2025). Abnormal cognition is characterized by deficits in thinking, reasoning, or remembering. "Knocking out the ALDH2 gene or overexpressing the inactive allele has been shown to induce cognitive impairment in mice, with increased 4-HNE deposition, amyloid-β (Aβ) accumulation, tau phosphorylation, and glial cells activation in mouse brain." (PMID 39290715, 2024). "The accumulation of FA in the brain of ALDH2–/– null mice was associated with hyperglycemia and cognitive impairment." (PMID 37693648, 2023). "We found that patients with ALDH2 gene genotypes of rs671_GG, rs886205_GG, rs4648328_CC, and rs4767944_TT polymorphisms were more likely to suffer from cognitive impairment during chemotherapy." (PMID 36200595, 2023). "Those with ALDH2 variants have greatly reduced ability to metabolise aldehydes and are more susceptible to cognitive impairment." (PMID 36200595, 2023). "This study indicated that patients with ALDH2 rs671_GG, rs886205_GG, rs4648328_CC, and rs4767944_TT polymorphisms were more likely to suffer from cognitive impairment during chemotherapy." (PMID 36200595, 2023). "We also applied a binary logistic regression model to evaluate the synergistic effects of ALDH2 polymorphisms and alcohol consumption on cognitive impairment." (PMID 34257742, 2021). "We demonstrated that ALDH2 polymorphisms and alcohol consumption had a synergistic effect on cognitive impairment, even after taking other potential risk factors into account (age, gender, education, and subtype)." (PMID 34257742, 2021). "Our results indicate that the association between alcohol consumption and cognitive impairment is stronger in the ALDH2 heterozygous group than in the wild-type genotype group, as well as with swallowing ability." (PMID 34257742, 2021). "We found that the ALDH2 mutant allele carried a higher risk of cognitive impairment using both MoCA cutoff scores." (PMID 34257742, 2021). "Using data from nearly 2,000 Chinese adults aged over 90 years, we found that the SNPs on ADH and ALDH2 genes were associated with higher odds of cognitive impairment." (PMID 35368830, 2021). "The Aldh2-/- mouse exhibits progressive, age-related cognitive deficits together with a constellation of AD-associated pathological changes rarely observed in current transgenic AD animal models." (PMID 25910195, 2015). "As an oxidative stress-based model of age-dependent cognitive impairment and neurodegeneration, the Aldh2-/- mice have distinct advantages over mice expressing the Glu504Lys mutation of ALDH2 (ALDH2*2)." (PMID 25910195, 2015). "The most common genetic mutation is ALDH2*2 associated with cognitive impairment." (PMID 37111618, 2023). "Similarly, at a cutoff MoCA score of 23, participants carrying the mutant ALDH2 allele also had a higher risk of cognitive impairment (OR = 2.65, 95%CI = 1.19–5.92, p < 0.05)." (PMID 34257742, 2021). "Moreover, after adjusting for other potential risk factors, ALDH2 polymorphisms and alcohol consumption had a significant synergistic effect on cognitive impairment (p = 0.022)." (PMID 34257742, 2021). "Thus, the effects of age and Aldh1a1/Aldh2-deficiency on spatial memory recapitulate the cognitive deficits seen in early stage Parkinson's disease." (PMID 22384032, 2012). "The ALDH2 rs671 (A) allele contributed to faster disease progression and hs-CRP mediated cognitive impairment in male ALS patients." (PMID 39290715, 2024). "Toxic aldehydes accumulated in ALDH2-deficient mice brains induce Aβ plaques and NFT formation associated with cognitive impairments." (PMID 37111618, 2023). "The results indicated that carrying the ALDH2 and ADH mutation was associated with higher odds of cognitive impairment among the oldest-old population." (PMID 35368830, 2021).
Cognitive impairment (continued). "In this study, we addressed the relationship between formaldehyde metabolism and cognitive disorders in children with sarcosinemia, AD dementia patients, and mice deficient in either SARDH (Sardh−/−) or ALDH2 (Aldh2−/−)." (PMID 31815201, 2019). "However, hydrogen sulfide, which induced an increase in ALDH2 expression, reduced the accumulation of reactive aldehydes in the brain and improved cognitive impairment in these rats." (PMID 37693648, 2023). "In patients with the ALDH2 heterozygous group, the multivariate OR (95% CI) of cognitive impairment risk compared with nondrinkers was 10.95 (1.04-114.88) in moderate drinkers." (PMID 34257742, 2021). "Among the oldest-old, carrying ALDH2 rs671 mutation was associated with higher odds of cognitive impairment independent of alcohol consumption." (PMID 35368830, 2021). "At a MoCA cutoff score of 26, the multivariate OR of cognitive impairment risk was 7.75 (95% CI: 1.03–113.78) for the ALDH2 wild-type genotype in excessive drinkers compared with nondrinkers." (PMID 34257742, 2021). "This difference in the subdomains of the cognitive impairment profiles compared to typical AD suggests that the mechanisms underlying the cognitive impairments in PD owing to reduced ALDH2 activity are not simply a combination of the deficits of PD and AD." (PMID 27453488, 2016). "Taken together these data suggest that not only is the ALDH2 pathway critical for the detoxification of HNE in the brain, but also that levels of toxic aldehydes derived from oxidative stress are sufficient to cause neuronal loss and cognitive impairment." (PMID 25910195, 2015). "The KSS-2 will determine how the genotypes (e.g., ALDH2, ADH1B, and APOE), SVD burden, and/or lifestyle factors interact with cognitive impairment, cerebral cardiovascular disease, and death." (PMID 40603063, 2025). "Silibinin increased the expression of ALDH2, GSH, and ADH3 proteins in the cortex of formaldehyde-induced cognitive impairment model mice." (PMID 35757504, 2022). "We have characterized a novel oxidative stress-based mouse model of cognitive impairment with AD-like biochemical and structural pathologies based on increased HNE formation due to the genetic deletion of ALDH2." (PMID 25910195, 2015). "We examined the associations of four single nucleotide polymorphisms (SNPs) on aldehyde dehydrogenase (ALDH) and alcohol dehydrogenase (ADH) genes (i.e., ALDH2 rs671, ADH1B rs1229984, ADH1B rs1042026, and ADH1C rs1693482) and cognitive impairment among the oldest-old." (PMID 35368830, 2021). "Therefore, silibinin improves the cognitive impairment of the FA model mice, and this may be related to the increase in ADH3 and ALDH2 enzyme activities." (PMID 35757504, 2022).
endothelial dysfunction (16 papers, 2012 to 2026). In vascular diseases, endothelial dysfunction is a systemic pathological state of the endothelium (the inner lining of blood vessels) and can be broadly defined as an imbalance between vasodilating and vasoconstricting substances produced by (or acting on) the endothelium. "The ALDH2*2 variant has been associated with several degenerative diseases, with evidence suggesting a link to cardiovascular disease, potentially mediated by endothelial dysfunction." (PMID 41364906, 2025). "Nitrate tolerance is accompanied by an increase in oxidative stress, endothelial dysfunction, and sympathetic activation, as well as a loss of the catalytic activity of ALDH2 itself." (PMID 36555095, 2022). "Our results demonstrate that in the vascular endothelium, loss of ALDH2 accelerates the acquisition of a premature senescence phenotype leading to endothelial dysfunction." (PMID 30538807, 2018). "By enhancing ALDH2 expression specifically in CVECs, we facilitate clearance of these toxic aldehydes, thus mitigating the cascade of oxidative injury that contributes to endothelial dysfunction and loss." (PMID 40723901, 2025). "It is reported that in the vascular endothelium, the loss of ALDH2 activity leads to endothelial dysfunction, as there is an increase in ROS levels, an accumulation of 4-hydroxy-2-nonenal (4-HNE) protein adducts, and a loss of mitochondrial bioenergetic functions." (PMID 36555095, 2022). "In addition, ALDH2-deficient mice exhibit significantly increased production of mitochondrial ROS and endothelial dysfunction after prolonged treatment with acetaldehyde." (PMID 31345174, 2019). "Due to the important role of ALDH2 in 4-HNE metabolism and in the 4-HNE-mediated oxidative stress in endothelial dysfunction, we speculate the ALDH2*2 polymorphism might affect the risk of ISR after PCI by influencing vascular endothelial function." (PMID 31345174, 2019). "Together, these results indicate that reduced ALDH2 activity leads to endothelial dysfunction, which is exacerbated by ethanol exposure." (PMID 37693648, 2023). "Today, it is known that endothelial dysfunction also involves the alteration of ALDH2 expression, thereby resulting in the alteration of the oxidative state and the onset of inflammation." (PMID 36555095, 2022). "ALDH2 overexpression prevented acetaldehyde-induced cell injury and decreased apoptosis in ECs and oxidative stress-induced endothelial dysfunction." (PMID 34764958, 2021). "Since senescence-related endothelial dysfunction plays a crucial role in the pathogenesis of several diseases, further studies are necessary to fully elucidate the role and protective mechanisms of ALDH2 in the endothelium." (PMID 31947800, 2020). "Studies from our laboratory have provided evidence on the contribution of ALDH2 to Aβ-induced endothelial dysfunction and on the possibility of preserving the endothelial function in some pathological conditions by activating the ALDH2 enzyme." (PMID 30538807, 2018). "Using mice carrying the human ALDH2*2 dysfunctional polymorphism, we demonstrated that this ALDH2*2 variant conferred susceptibility to HS, as evidenced by increased ROS and 4-HNE accumulation, vascular inflammation and endothelial dysfunction." (PMID 34764958, 2021). "Twenty minutes of forearm ischemia induced significant endothelial dysfunction in individuals with (p < 0.0001, n = 9) or without (p = 0.0001, n = 9) the ALDH2*2 allele." (PMID 28280793, 2017). "In addition, endothelial dysfunction and hypercontractility was clearly evident in Aldh2-/- mice, as indicated by the reduced aortic relaxation responses to acetylcholine (ACh), and enhanced contractile responses to the adrenoceptor agonist, phenylephrine." (PMID 25910195, 2015).
endothelial dysfunction (continued). "Endothelial dysfunction and hypercontractility were clearly evident in Aldh2-/- mice, as indicated by the reduced aortic relaxation responses to acetylcholine that are dependent on endothelial NO release, and by enhanced contractile responses to the adrenoceptor agonist, phenylephrine." (PMID 25910195, 2015). "Although their involvement in the context of AD has not yet been directly determined, endothelial dysfunction due to reduced ALDH2 activity and its exacerbation by ethanol likely contribute to the pathogenesis of AD." (PMID 37693648, 2023). "Prior systemic ALDH2 gene transfer studies demonstrated cardioprotection against ischemia/reperfusion injury by lowering 4HNE levels, but the current CVEC-focused strategy addresses the emerging paradigm that endothelial dysfunction and capillary rarefaction are central to HFpEF pathology." (PMID 40723901, 2025).
leukemia (15 papers, 2017 to 2025). A malignant (clonal) hematologic disorder, involving hematopoietic stem cells and characterized by the presence of primitive or atypical myeloid or lymphoid cells in the bone marrow and the blood. "In view of the effect of ALDH2 on mitochondrial biogenesis and mitochondrial respiration, we investigated the effect of ALDH2 on leukaemia proliferation and the underlying mechanism in mice in vivo." (PMID 40796730, 2025). "Based on these findings, we postulate that ADH5 and ALDH2 inhibitors enhance the synthetically lethal effect of Polθi against HR-deficient leukemia cells." (PMID 40640557, 2025). "We also demonstrate that simultaneous targeting of Polθ and ADH5 or ALDH2 may have therapeutic potential in HR-deficient leukemias, and those harboring high levels of endogenous formaldehyde triggered by OTKs." (PMID 40640557, 2025). "Similarly, in mouse models of FA, mice with only Fancd2 mutations exhibit a long latency to developing mild hematopoietic stem cell dysfunction, but adding an Adh5 or Aldh2*2 mutation results in bone marrow failure and leukemia." (PMID 40244696, 2025). "Disulfiram (DSF) is an aldehyde dehydrogenase inhibitor that can inhibit the expression of ALDH2 and improve the sensitivity of leukaemia stem cells to chemotherapy drugs." (PMID 40796730, 2025). "Loss or insufficient activity of ALDH2 and ADH5, which both metabolize formaldehyde, has been linked to early bone marrow failure and the spontaneous development of leukemia in mice and humans with FA pathway deficiency, resulting in a DNA repair defect." (PMID 41292832, 2025). "We postulate that the interdependence between Polθ and ALDH2/ADH5 in protecting leukemia cells from high levels of endogenous formaldehyde creates a translational opportunity." (PMID 40640557, 2025). "Monitoring of the tumour volume and weight of the mice revealed that ALDH2 significantly promoted the growth and proliferation of leukaemia cells and significantly increased resistance to Ara-C treatment." (PMID 40796730, 2025). "The overexpression of ALDH2 significantly increased the proliferation rate and the ability to form colonies in leukemia cell lines, resulting in increased resistance to doxorubicin." (PMID 38254953, 2023). "ALDH2, the aldehyde dehydrogenase in the mitochondria of leukemia cells that suppresses formaldehyde accumulation, was closely related to AML relapse." (PMID 36338749, 2022). "We found that the levels of ALDH2 mRNA are particularly low in melanoma, sarcoma, leukaemia and bladder cancer." (PMID 30088263, 2018). "In view of the influence of mitochondrial respiration on the growth and proliferation of leukaemia cells, we also examined the colony formation ability of AML cells after treatment with Nrf2 and ALDH2." (PMID 40796730, 2025). "Animal experiments confirmed that mice lacking ADH5 and ALDH2 have greatly shortened lifespans and develop leukemia in vivo." (PMID 34778061, 2021). "Without enzymes that detoxify formaldehyde, specifically ALDH2 and ADH5, hematopoietic cells die or transform into leukemia." (PMID 41292832, 2025). "Mice lacking both ALDH2 and ADH5 develop leukaemia and have shorter lifespans, and, despite active DNA repair, bone marrow-derived progenitors acquire a formaldehyde-associated mutation signature that resembles human cancer mutation signatures associated with aging." (PMID 35485397, 2022).